OLA1 (Obg like ATPase 1)
Diseases named in the same sentence as OLA1 in open-access papers (continued):
Sharing a sentence is not in itself a finding about the gene and the disease.
atherosclerosis (2 papers, 2022 to 2024). A disease characterized by the build-up of fatty material and calcium deposition in the arterial wall resulting in partial or complete occlusion of the arterial lumen. "Recent studies have also reported mutations in the OLA1 gene associated with the incidence of atherosclerosis in humans." (PMID 38889130, 2024). "Here, we conducted two independent population-based case–control studies to explore the effects of variants in OLA1 genes on preclinical atherosclerosis." (PMID 36232807, 2022). "Additionally, research involving atherosclerosis patients has revealed several mutations in the OLA1 gene, with five of them exhibiting a strong association with the development of atherosclerosis." (PMID 38889130, 2024). "Based upon the previous observations and our observations in this study, several lines of evidence reveal that the genetic variants in OLA1 may correlate with the development of atherosclerosis." (PMID 36232807, 2022). "Therefore, vascular EC- or SMC-specific inducible OLA1 knockout mice are needed to verify whether loss of OLA1 in vascular ECs or SMCs may cause development of atherosclerosis in mice." (PMID 36232807, 2022). "Similarly, vascular EC- or SMC-specific inducible OLA1-overexpressing mice are also needed to verify whether overexpression of OLA1 in vascular ECs or SMCs may cause development of atherosclerosis in mice." (PMID 36232807, 2022). "The second line of evidence is that OLA1 interacts with several proteins involved in the development of atherosclerosis." (PMID 36232807, 2022). "In this study, we found that OLA1 was required for migration and proliferation of human aortic SMCs, suggesting that OLA1 should play a role in the development of atherosclerosis." (PMID 36232807, 2022). "However, to our knowledge, there are no reports on OLA1 association with preclinical traits of atherosclerosis or cardiovascular events." (PMID 36232807, 2022). "Further, given that OLA1 and BRCA1 regulate the cellular responses to oxidative stresses, it can be speculated that OLA1 and BRCA1 work together in the development of atherosclerosis." (PMID 36232807, 2022). "However, it is not known whether OLA1 is genetically correlated with atherosclerosis." (PMID 36232807, 2022).
lung adenocarcinoma (2 papers, 2016 to 2020). A carcinoma that arises from the lung and is characterized by the presence of malignant glandular epithelial cells. "Knockdown of OLA1 in lung adenocarcinoma cells can attenuate the TGF-β-induced EMT process and restore E-cadherin expression." (PMID 32528278, 2020). "We further evaluated the OLA1 expression in larger tissue sections cut from formalin-fixed paraffin-embedded tumor and paired normal lung tissues from 10 patients with lung adenocarcinoma." (PMID 26863455, 2016). "Knockdown of OLA1 in a lung adenocarcinoma cell line rendered the cells more resistant to TGF- β-induced EMT and the accompanied repression of E-cadherin." (PMID 26863455, 2016). "However, our meta-analysis showed that the high-expression OLA1 was significantly associated with poor OS in lung adenocarcinoma patients but not in squamous carcinoma patients." (PMID 26863455, 2016).
oral cancer (2 papers, 2020 to 2021). "We tried to make an orthotopic oral cancer metastasis model to verify the inhibitory effect of OLA1 on oral cancer metastasis by inoculating human oral cancer metastasis cell line UM-1 in nude mice." (PMID 32928102, 2020). "When we knocked down or elevated the level of OLA1 in oral cancer cells UM-1 and UM-2, the phenotype of the cells changed significantly with a more EMT/MET (mesenchymal epithelial transition) status." (PMID 32928102, 2020). "A series of in vitro assays were performed in the cells with RNAi-mediated knockdown or overexpression to expound the regulatory function of OLA1 in oral cancer." (PMID 32928102, 2020). "Our work indicated that OLA1 expression in oral cancer cells was significantly lower than that of normal oral cells, and decreased as the degree of cancer metastasis increases." (PMID 32928102, 2020). "Meanwhile, E-cadherin was significantly down-regulated in the oral cancer cells with OLA1-knocked down, suggesting that OLA1 inactivated EMT process." (PMID 32928102, 2020). "We found that the wound healing ability of oral cancer cells was much higher in OLA1 silenced oral cells as compared to control." (PMID 32928102, 2020). "The metastatic ability of oral cancer cells was also much higher in the OLA1 silenced oral cancer cells than the control cells." (PMID 32928102, 2020). "Therefore, we plan to use OLA1(−/−) systemic knockout mice to further study the function of OLA1 in inhibiting oral cancer metastasis using a drug-induced oral carcinoma in situ in the future." (PMID 32928102, 2020). "These evidences indicated that OLA1 may increase the sensitivity of cells to drugs by reducing the migration of oral cancer cells, thus playing an anti-tumor role." (PMID 32928102, 2020). "It was further demonstrated by the scratch test and the Transwell experiment that OLA1 could substantially inhibit the metastasis and invasion of oral cancer." (PMID 32928102, 2020). "Our data suggests that OLA1 may be developed as a potential target for the treatment of oral cancer metastasis." (PMID 32928102, 2020). "It showed that OLA1 could increase the sensitivity of oral cancer cells to PTX." (PMID 32928102, 2020). "Therefore, we report that OLA1 can inhibit the EMT process induced by TGFβ/SMAD2, thereby increasing the drug sensitivity of oral cancer cells to PTX." (PMID 32928102, 2020). "Previously, although there are a few studies showing the involvement of OLA1 in tumor metastasis, the exact role of OLA1 in oral cancer metastasis is not known yet." (PMID 32928102, 2020). "We found that OLA1 expression in metastasis cell line UM-1 was significantly lower than the carcinoma in situ cell line UM-2, suggesting a negative role OLA1 playing in oral cancer metastasis." (PMID 32928102, 2020). "We observed that OLA1 may play a negative role in the metastasis and invasion of oral cancer and this effect may be achieved through the EMT pathway, which plays a vital role in the diagnosis and treatment of clinical oral cancer." (PMID 32928102, 2020).
Arrhythmia (1 paper, 2024). Any cardiac rhythm other than the normal sinus rhythm. "Vitexin could reduce aging and arrhythmia through OLA1-Nrf2 signaling pathway." (PMID 39381749, 2024).
Babesia infection (1 paper, 2020). "In addition, our results indicate that ola1, crt, and vitellogenin family proteins such as Vg1, Vg2 may have important roles in blood feeding and Babesia infection in H. longicornis female ticks." (PMID 32423088, 2020).
breast invasive carcinoma (1 paper, 2020). "Notably, the Kaplan-Meier (KM) Plotter analysis showed that OLA1 expression may negatively correlate with the overall survival and relapse free survival of breast invasive carcinoma (BRCA) patients." (PMID 32528278, 2020).
cardiomyopathy (1 paper, 2024). A disease of the heart muscle or myocardium proper. "Our results demonstrate that this PCR test can effectively screen for OLA1 mutation-associated cardiomyopathy in human patients using easily accessible cells or tissues, such as blood cells." (PMID 38889130, 2024).
colitis (1 paper, 2025). Inflammation of the colon. "OLA1 provides a molecular mechanism for a new therapeutic strategy for colitis and related systemic inflammations." (PMID 40725244, 2025).
familial dilated cardiomyopathy (1 paper, 2024). A a genetic form of heart disease that occurs when heart (cardiac) muscle becomes thin and weakened in at least one chamber of the heart, causing the open area of the chamber to become enlarged (dilated). "The human OLA1 gene maps to chromosome 2 (locus 2q31.1), near Titin (TTN), which is associated with familial dilated cardiomyopathy (DCM)." (PMID 38889130, 2024). "OLA1 maps to chromosome 2 (locus 2q31.1), near Titin (TTN), which is associated with familial dilated cardiomyopathy (DCM) in humans." (PMID 38889130, 2024).
heart failure (1 paper, 2024). Inability of the heart to pump blood at an adequate rate to meet tissue metabolic requirements. "In summary, our findings shed light on the potential role of OLA1 in cardiac physiology and underscore the significance of OLA1 mutations in heart failure." (PMID 38889130, 2024). "To investigate the potential association between OLA1 mutations and heart failure, we compiled complete OLA1 gene sequences from each patient and aligned them using MegAlign to identify genetic variations." (PMID 38889130, 2024). "In this investigation, we screened for mutations in the OLA1 gene and explored their association with heart failure in humans." (PMID 38889130, 2024). "The effects of OLA1 mutations on heart failure in human patients are yet to be extensively studied." (PMID 38889130, 2024). "This test should help in the further investigation of the role of OLA1 in heart failure and develop therapeutic approaches in such cases." (PMID 38889130, 2024). "Alterations in the expression of OLA1 have been identified in samples from patients with heart failure, as well as in the cardiac tissue of mice following ANGII administration." (PMID 38889130, 2024). "In this study, we sought to screen for mutations in the OLA1 gene among failing and non-failing patients and investigate their association with heart failure." (PMID 38889130, 2024). "Although mutations in more than 40 genes are known to cause DCM in humans, it is not known if mutations in the OLA1 gene have any direct role in human heart failure." (PMID 38889130, 2024).
Hepatitis (1 paper, 2025). Inflammation of the liver. "The differences in anti-OLA1 autoantibody levels between healthy control and hepatitis control were compared, revealing no significant statistical differences between the two groups." (PMID 41246329, 2025).
liver cancer (1 paper, 2025). An epithelial or non-epithelial malignant neoplasm that arises from the liver. "The positive correlation between OLA1 and B cells suggests that OLA1 overexpression in the liver cancer microenvironment may stimulate B cells to produce anti-OLA1 autoantibody." (PMID 41246329, 2025).
lymph node metastasis (1 paper, 2016). "Moreover, high-expression OLA1 was found more often in cases with lymph node metastasis than in cases without lymph node metastasis (42.9% vs.20.4%, p = 0.01)." (PMID 26863455, 2016).
multiple sclerosis (1 paper, 2016). A progressive autoimmune disorder affecting the central nervous system resulting in demyelination. "Croze indicated that OLA1 down-regulation is a plausible mediator of neuronal preservation, which was implicated in optic neuropathy and multiple sclerosis-like lesions." (PMID 26745496, 2016).
respiratory failure (1 paper, 2020). The significant impairment of gas exchange within the lungs resulting in hypoxia, hypercarbia, or both, to the extent that organ tissue perfusion is severely compromised. "Notably, Ola1 KO mice show strikingly similar phenotypes as those of Gcn1ΔRWDBD mice (i.e., embryonic growth retardation and perinatal lethality due to respiratory failure)." (PMID 32324833, 2020).
squamous cell carcinoma (1 paper, 2016). A carcinoma arising from squamous epithelial cells. "The frequency of high-expression OLA1 was significantly higher in squamous cell carcinoma (56.1%, 23 of 41) than that in other histological types (17.4%, 12 of 69) (p < 0.0001)." (PMID 26863455, 2016).
cancer (22 papers, 2015 to 2025). A tumor composed of atypical neoplastic, often pleomorphic cells that invade other tissues. "One hallmark of human OLA1 is that it is upregulated in many cancer cells and that both metastasis and long-term survival are influenced by the Ola1 levels." (PMID 38993675, 2024). "Tumour formation is at least partially linked to changes in Ser/Thr phosphorylation of some cancer-related proteins upon increased Ola1-levels." (PMID 35056463, 2021). "The universally conserved P-loop ATPase Ola1 is implicated in various cellular stress response pathways, as well as in cancer and tumor progression." (PMID 34571008, 2021). "In vivo, OLA1-knockdown rendered cancer cells deficient in ISR and the downstream proapoptotic effector, CHOP, promoting tumor growth and metastasis." (PMID 26283179, 2015). "Our patient-based study furnished evidence that lower OLA1 expression is associated with a higher chance of cancer relapse and worse DSS." (PMID 26283179, 2015). "We further demonstrated that a hypoactive ISR status, mediated by knockdown (KD) of OLA1, was associated with the increased survival of cancer cells challenged with multiple stresses in vitro, and more strikingly, advanced tumor growth and metastasis in vivo." (PMID 26283179, 2015). "In bacteria, yeast, plants, and mammals, YchF/Ola1 has been linked to multiple stress response mechanisms and its overproduction is observed in multiple types of cancer and potentially associated with poor survival rates in human cancer patients." (PMID 38993675, 2024). "The IMP2-ZFAS1-OLA1 axis is instrumental in CRC progression by stabilizing ZFAS1 and enhancing OLA1 activity, which in turn accelerates glycolytic metabolism and supports cancer cell proliferation and survival." (PMID 40141058, 2025). "In cancer cells, increased expression of OLA1 inhibits apoptosis by interacting with breast cancer-associated gene 1 (BRCA1) and BRCA1-associated RING domain protein (BARD1)." (PMID 38889130, 2024). "The elevated expression of OLA1 in cancer cells has been correlated with poor survival and clinical outcomes." (PMID 38889130, 2024). "Increased expression of OLA1 in cancer cells appears to enhance their survival by interacting with BRCA1 and BRCA1-associated RING domain proteins (BARD1)." (PMID 38889130, 2024). "Studies in human cancer have shown that increased expression of OLA1 correlated with swift disease progression and unfavorable prognosis." (PMID 38889130, 2024). "Considering the documented connection between Ola1 levels and cancer, these studies will be particularly important for developing Ola1 as a potential therapeutic target." (PMID 35056463, 2021). "OLA1 mediates the phosphorylation of serine and threonine on proteins in cancer cells by restraining the GSK3β-inhibitor 2-PP1 positive feedback loop, leading to more aggressive tumor growth." (PMID 32045367, 2020). "The human Obg-like ATPase 1 (OLA1) protein has been reported to play an important role in cancer cell proliferation." (PMID 32928102, 2020). "This study provides the first evidence for the existence of a GSK3β-I-2-PP1 positive feedback loop in human cancer cells, and identifies OLA1 as an endogenous suppressor of this signaling motif." (PMID 26655089, 2016). "When several human cancers were compared to their normal tissue counterparts, OLA1 mRNA was actually increased in ≥50% of samples." (PMID 26655089, 2016). "In our previous studies, OLA1 knockdown cancer cells exhibited decreased cell migration and invasiveness, and enhanced cell-matrix adhesion." (PMID 26863455, 2016). "Next, we performed IHC staining for the EMT marker E-cadherin with tissue sections made from the same-tissue array and analyzed the correlation of OLA1 with E-cadherin among all 110 cancer cases." (PMID 26863455, 2016). "This study shows the first direct evidence for the existence of a GSK3β-PP1 positive feedback loop in a cancer signaling network, and presents a novel endogenous suppressor of that loop, OLA1." (PMID 26655089, 2016).
cancer (continued). "It is possible that the OLA1-KD-mediated increased survival renders cancer cells able to overcome these rate-limiting steps of metastasis." (PMID 26283179, 2015). "Future studies are warranted to delineate the mechanisms that mediate OLA1 downregulation and cancer relapse — for example, the development of resistance to post-surgery chemotherapy, or a switch between cancer dormancy and recurrence." (PMID 26283179, 2015). "These OLA1-KD cancer cells also showed increased survival under TM treatment, prolonged serum starvation, and total AA starvation." (PMID 26283179, 2015). "Our work suggests that OLA1 is a novel translational GTPase and plays a suppressive role in translation and cell survival, as well as cancer growth and progression." (PMID 26283179, 2015). "OLA1 has been shown to play a pivotal role in the progression of cancer and heart disease." (PMID 38889130, 2024). "The prevalence of OLA1 upregulation raises an intriguing possibility that OLA1 overexpression may be a cancer-promoting event in CRC." (PMID 35440019, 2022). "Furthermore, OLA1 is overexpressed in various cancers, which underscores the interest in better understanding Ola1/YchF functions." (PMID 34571008, 2021). "OLA1 overexpression has been detected in multiple types of cancer and may be related to poor survival." (PMID 32045367, 2020). "The results of OLA1 expression and functions analysis in metastasis were from different cancer types, which may be the reason for the inconsistency." (PMID 32928102, 2020). "Studies have revealed that the modulation of OLA1 in tumorigenesis may be two-sided, either inhibitory or promoting the cancer." (PMID 32045367, 2020). "In summary, the exact regulatory role of OLA1 in cancer is still unknown." (PMID 32928102, 2020). "However, the role of OLA1 in cancer progression remains poorly understood." (PMID 26863455, 2016). "Significantly elevated levels of anti-OLA1 autoantibody were observed in both ANHCC and APHCC patients compared to healthy controls or non-cancer controls across all three centers, with all P-values< 0.05." (PMID 41246329, 2025). "OLA1 is significantly expressed in HCC, and knockdown of this gene suppresses the progression of cancer cells." (PMID 40636922, 2023). "The other hub genes (e.g., YBX1, OLA1, TRMT10C, and KIF20A) also play a key role in the development and prognosis of the pan-cancer section." (PMID 35720008, 2022). "We also examined eIF2α, GSK3β, and I-2 in the second cancer line (SKOV3), and obtained the same results: they were all under-phosphorylated in the OLA1-KD cells as compared with the control cells." (PMID 26655089, 2016). "Cancer-derived variants of BRCA1, BARD1, OLA1, and RACK1 failed to interact, and aberrant expression of these proteins caused centrosome amplification due to centriole overduplication only in mammary tissue-derived cells." (PMID 32722046, 2020). "In our studies, we compared OLA1-KD cancer cells to control cells without comparison to any noncancerous cells." (PMID 26655089, 2016). "Of the 110 cancer samples, 83 were positive for OLA1 expression in the cytoplasm, whereas none of the 10 normal lung tissues showed detectable OLA1 (p < 0.0001)." (PMID 26863455, 2016). "OLA1 has been reported to be connected with cell cycle as well as apoptosis in HCC, which promotes tumor development by binding with p21 and stimulating the expression of CDK2, knocking down its expression contributes to G0/G1 phase arrest and enhancing apoptosis of cancer cells." (PMID 36463115, 2022).